ZNF674 (zinc finger protein 674)
Description:
May be involved in transcriptional regulation.
Synonyms: ZNF673B; MRX92
Tractability: PROTAC: ubiquitination databases record sites on it.
Gene: Protein-coding gene on chromosome X (46,497,725 to 46,545,457, reverse strand). Ensembl gene ENSG00000251192.
Subcellular location: Nucleus
Subcellular location (Human Protein Atlas): Nucleoplasm
Gene Ontology:
Molecular function: DNA-binding transcription factor activity, RNA polymerase II-specific; RNA polymerase II transcription regulatory region sequence-specific DNA binding
Biological process: regulation of transcription by RNA polymerase II; regulation of DNA-templated transcription
Cellular component: nucleoplasm; nucleus
Gene-disease validity (ClinGen):
ClinGen rates the evidence that ZNF674 causes each of these diseases.
X-linked intellectual disability (X-linked): Disputed. An X-linked intellectual deficiency in which not enough information is known, reported or published to indicate whether a gene causes non-syndromic or syndromic presentations.
Homologues: Orthologues: chimpanzee ZNF674 (99% identical), macaque ZNF674 (94% identical), dog ZNF674 (80% identical), pig ZNF674 (72% identical), mouse Zfp78 (35% identical), Drosophila melanogaster CG3281 (23% identical), Drosophila melanogaster CG2712 (20% identical), Drosophila melanogaster Phs (19% identical). Paralogues in human: ZNF614 (43% identical), ZFP90 (42% identical), ZFP37 (38% identical), ZNF133 (37% identical), ZNF10 (37% identical), ZNF25 (37% identical), ZNF248 (37% identical), ZNF805 (37% identical), ZNF555 (36% identical), ZNF266 (36% identical), ZNF749 (36% identical), ZNF582 (35% identical), and 50 more.